HSPB9 (heat shock protein family B (small) member 9)
Synonyms: CT51
Tractability: No criterion of Open Targets' tractability assessment is met for any kind of drug.
Gene: Protein-coding gene on chromosome 17 (42,122,804 to 42,123,352, forward strand). Ensembl gene ENSG00000260325.
Subcellular location: Cytoplasm; Nucleus
Subcellular location (Human Protein Atlas): Nucleoplasm; Cytosol; Vesicles
Gene Ontology:
Molecular function: protein binding
Cellular component: cytoplasm; cytosol; nucleoplasm; nucleus
Genetic constraint (gnomAD): Loss-of-function variants: 0 observed, 0.12 expected, observed/expected ratio (o/e) 0, 90% interval 0 to 1.89. That is too few expected variants to judge how well the gene tolerates losing a copy. Missense variants: 203 observed, 222.99 expected, observed/expected ratio (o/e) 0.91, 90% interval 0.81 to 1.02. Synonymous variants: 98 observed, 97.55 expected, observed/expected ratio (o/e) 1, 90% interval 0.85 to 1.19.
Homologues: Orthologues: chimpanzee HSPB9 (97% identical), rabbit HSPB9 (66% identical), pig HSPB9 (63% identical), rat Hspb9 (60% identical), mouse Hspb9 (59% identical), guinea pig HSPB9 (51% identical), tropical clawed frog hsp30e (19% identical), zebrafish hspb9 (19% identical), zebrafish hspb9l (18% identical), Drosophila melanogaster Hsp67Ba (18% identical), Drosophila melanogaster l(2)efl (18% identical), tropical clawed frog hsp30c (18% identical), and 14 more. Paralogues in human: CRYAA (21% identical), CRYAB (19% identical), HSPB6 (19% identical), HSPB1 (18% identical), HSPB3 (15% identical), HSPB8 (14% identical), HSPB2 (14% identical), HSPB7 (13% identical).
Diseases named in the same sentence as HSPB9 in open-access papers:
HSPB9 is named in the same sentence as 11 diseases in open-access papers, as found by Europe PMC text mining. Sharing a sentence is not in itself a finding about the gene and the disease. The quoted sentences say what the papers report.
Arrhythmia (1 paper, 2024). Any cardiac rhythm other than the normal sinus rhythm. "Eight of these associations were novel (LMNA, SMAD6, HSPB9, TMEM95, KLF1, TET2, NME3, KDM5B) and 5 genes have previously been linked to arrhythmias (SCN5A, TTN, RPL3L, PKP2, PMVK)." (PMID 38390584, 2024).
conduction disorders (1 paper, 2024). "Rare variations in 5 genes were linked to conduction disorders (SCN5A, LMNA, SMAD6, HSPB9, TMEM95)." (PMID 38390584, 2024).
Left bundle branch block (1 paper, 2024). A conduction block of the left branch of the bundle of His. "One previously GWAS-linked gene (SCN5A) and 3 novel genes (LMNA, SMAD6, HSPB9) were identified for atrioventricular and left bundle branch block (ICD10 code I44)." (PMID 38390584, 2024).
cancer (2 papers, 2020 to 2022). A tumor composed of atypical neoplastic, often pleomorphic cells that invade other tissues. "HSPB10 ectopic expression has also been found in some cancers, suggesting that, as HSPB9, it should be evaluated as a cancer biomarker." (PMID 35281256, 2022). "For example, in the HSP20 family, HSPB7 was positively enriched in 22 cancer types, while HSPB9 was negatively enriched in 25 cancer types." (PMID 33225964, 2020). "HSPB9 has been also detected in tumors, suggesting HSPB9 as a candidate Cancer/Testis Antigen." (PMID 35281256, 2022). "Studies on HSPB9 oligomerization are missing, but yeast two-hybrid screening revealed its interaction through the CTD with the t-complex testis expressed protein-1, a light chain subunit of dynein, which also follows a similar expression pattern in testis and cancers." (PMID 35281256, 2022).
tumours (1 paper, 2018). "Incremented transcripts levels of HSPB1, HSPB9 and HSPB11 were observed in most BRCA subtypes, CRYAA was upregulated only in Basal subtype and ODF1 showed an increased expression in Luminal A tumours that was not significant by the Deseq2 method." (PMID 29954368, 2018).
HSPB9 also shares sentences with these, for which no sentence is quoted: amyloidosis (2 papers); bladder cancer (1); cataract (1); distal hereditary motor neuropathy (1); heart conduction disorders (1); neuropathy (1).